COMMD8 (COMM domain containing 8)
Description:
Scaffold protein in the commander complex that is essential for endosomal recycling of transmembrane cargos; the commander complex is composed of the CCC subcomplex and the retriever subcomplex. May modulate activity of cullin-RING E3 ubiquitin ligase (CRL) complexes. May down-regulate activation of NF-kappa-B.
Synonyms: FLJ20502
Tractability: PROTAC: ubiquitination databases record sites on it; its protein half-life has been measured.
Gene: Protein-coding gene on chromosome 4 (47,450,787 to 47,463,730, reverse strand). Ensembl gene ENSG00000169019.
Subcellular location: Cytoplasm; Nucleus
Subcellular location (Human Protein Atlas): Cytosol; Nucleoplasm
Pathways (Reactome):
Metabolism of proteins: Neddylation
Gene Ontology:
Molecular function: protein binding; NF-kappaB binding
Biological process: endocytic recycling; signal transduction
Cellular component: cytoplasm; cytosol; nucleoplasm; nucleus; protein-containing complex; endoplasmic reticulum membrane; endosome membrane
Genetic constraint (gnomAD): Loss-of-function variants: 13 observed, 15.09 expected, observed/expected ratio (o/e) 0.86, 90% interval 0.56 to 1.37. The upper end of that interval is the gene's LOEUF score, 1.37, which puts it in group 5 of 6, group 1 being the genes least tolerant of losing a copy. Missense variants: 148 observed, 138.12 expected, observed/expected ratio (o/e) 1.07, 90% interval 0.94 to 1.23. Synonymous variants: 58 observed, 47.05 expected, observed/expected ratio (o/e) 1.23, 90% interval 1 to 1.53.
Homologues: Orthologues: chimpanzee COMMD8 (100% identical), macaque COMMD8 (96% identical), dog COMMD8 (86% identical), pig COMMD8 (83% identical), rabbit COMMD8 (83% identical), guinea pig COMMD8 (81% identical), mouse Commd8 (77% identical), rat Commd8 (72% identical), tropical clawed frog commd8 (56% identical), zebrafish commd8 (47% identical). Paralogues in human: COMMD7 (13% identical), COMMD6 (11% identical).
Diseases named in the same sentence as COMMD8 in open-access papers:
COMMD8 is named in the same sentence as 11 diseases in open-access papers, as found by Europe PMC text mining. Sharing a sentence is not in itself a finding about the gene and the disease. The quoted sentences say what the papers report.
hepatocellular carcinoma (3 papers, 2020 to 2023). A malignant tumor that arises from hepatocytes. "MNX-AS1 was reported to act as a functional oncogene that induces aggressiveness by numerous manners such as activating MAPK pathway in cervical cancer and acting as a sponge to miR-218-5p/COMMD8 axis in hepatocellular carcinoma and to miR-34a/SIRT1 axis in esophageal squamous cell carcinoma." (PMID 32754442, 2020).
non-small cell lung carcinoma (2 papers, 2021 to 2022). A group of at least three distinct histological types of lung cancer, including non-small cell squamous cell carcinoma, adenocarcinoma, and large cell carcinoma. "lncRNA MALAT1 aggravates the progression of non-small cell lung cancer by stimulating COMMD8 expression by targeting miRNA-613, and the tumorigenicity of MALAT1 has been verified in vivo." (PMID 35706002, 2022). "The mRNA expression levels of COMMD3, COMMD4, COMMD5, COMMD6, and COMMD8 were also significantly downregulated in non-small cell lung cancer (NSCLC) cell lines, whereas COMMD9 was up-regulated and promotes the development of NSCLC by interacting with the TFDP1/E2F1 through the COMM domain." (PMID 33768002, 2021).
gastric cancer (1 paper, 2023). A primary or metastatic malignant neoplasm involving the stomach. "Recent studies demonstrated that miR-218-5p served as a tumor suppressor to inhibit tumor growth and development by targeting endoplasmic reticulum oxidoreductase one alpha (ERO1A), COMMD8, CDK6, and EGFR in lung, liver, and gastric cancer." (PMID 36831545, 2023).
prostate carcinoma (1 paper, 2020). A carcinoma that arises from epithelial cells of the prostate gland. "RT-qPCR analysis show that ADAM10, ARMC8, COMMD8, EEA1 and PPM1B were expressed at similar levels in prostate cancer cells transfected with ZBTB38 and control siRNAs suggesting that these genes are not regulated by ZBTB38, but rather co-regulated by a common upstream factor and/or pathway." (PMID 32365491, 2020).
cancer (4 papers, 2021 to 2023). A tumor composed of atypical neoplastic, often pleomorphic cells that invade other tissues. "For instance, MALAT1 knockdown through siRNA has been reported to block cancer cell proliferation and reduce tumour growth in NSCLC by downregulating COMMD8." (PMID 35379783, 2022).
COMMD8 also shares sentences with these, for which no sentence is quoted: tumor (3 papers); cervical cancer (1); esophageal squamous cell carcinoma (1); glioma (1); lung carcinoma (1); neurodegenerative disease (1).